CBS (cystathionine beta-synthase)
Diseases named in the same sentence as CBS in open-access papers (continued):
Sharing a sentence is not in itself a finding about the gene and the disease.
homocystinuria (continued). "Classical homocystinuria (HCU; OMIM# 236200) is a rare inborn error of sulfur amino acid metabolism caused by substantially reduced or entirely missing cystathionine beta-synthase (CBS) activity." (PMID 32971905, 2020). "Betaine anhydrous (Cystadane®, Orphan Europe) is a methylating agent approved for the treatment of homocystinuria involving CBS, MTHFR or cbl defects." (PMID 30871635, 2019). "Plasma from patients with vitamin B6-responsive cystathionine β-synthase (CBS, B6-responsive, classic homocystinuria) showed near normal values in agreement with the positive response to treatment of this CBS subtype." (PMID 31635306, 2019). "A novel therapeutic approach is currently under development based on enzyme replacement therapy using PEGylated recombinant CBS, which has been shown to afford a marked decrease in circulating homocysteine in a mouse model of homocystinuria." (PMID 28421128, 2017). "Cystathionine beta-synthase (CBS) deficiency is a rare inherited disorder, also known as classical homocystinuria (OMIM 236200)." (PMID 27778219, 2017). "Cystathionine β-synthase (CBS) deficiency (MIM# 236200, also known as homocystinuria due to CBS deficiency) is a well-known multisystemic inborn error of metabolism with widely varying estimates of frequency." (PMID 20506325, 2010). "Classical homocystinuria (MIM# 236200), also known as homocysteinemia type 1, is a rare congenital metabolic disorder caused by deficiency of cystathionine β-synthase (CBS), an enzyme that catalyzes the transsulfuration of homocysteine (Hcy) to cystathionine with the help of its cofactor pyridoxine." (PMID 40299504, 2025). "Spectrum of genetic variants in CBS gene and their correlation with the phenotypes of homocystinuria in Sri Lankan patients have not been reported to date." (PMID 39839200, 2025). "Because of the close relationship between homocystinuria and cancer, CBS plays a significant pathogenetic role in cancer and is linked to metastasis and multidrug resistance owing to the important regulatory effect of H2S on mammalian biology, physiology, and pathophysiology." (PMID 38022516, 2023). "Interestingly, the vision phenotype of CBS knock-down flies is consistent with severe myopia observed in homocystinuria patients." (PMID 35740876, 2022). "Consequently, an impaired CBS activity leads to the elevation of both the methionine and homocysteine levels in the blood and urine, leading to hyperhomocysteinemia, homocystinuria, hypermethioninaemia, and hypocysteinaemia." (PMID 32245022, 2020). "The spectrum of CBS gene variants in Indian children with classical homocystinuria has not been reported to date." (PMID 33057012, 2020). "Details of CBS gene variants and MTHFR C677T polymorphism of 14 classical homocystinuria cases." (PMID 33057012, 2020). "Indeed, dietary manipulation of folates results in altered hematopoiesis, and dysregulation of this pathway owing to dosage increase of cystathionine beta synthase in Down syndrome results in macrocytic anemia and homocystinuria." (PMID 31207887, 2019). "The two phenotypic variants of CBS deficiency are B6-responsive and B6-non-responsive homocystinuria, where mutations in the CBS gene cause a varying response to vitamin B6." (PMID 30871635, 2019). "CBS deficiency should be considered in the differential diagnosis, even if the patient shows no other clinical features of classical homocystinuria." (PMID 27778219, 2017). "Homocystinuria is a rare (1:250,000) autosomal-recessive disorder caused by an absence of the enzyme cystathionine β-synthase (CBS)." (PMID 28774346, 2017). "A mouse model of HCU (CBS-deficient homocystinuria) did not exhibit hepatopathy due to the induction of ER stress by homocysteine probably due to the protective effects of cystathionine." (PMID 26959487, 2016).
homocystinuria (continued). "Though the in vitro Hcy concentrations used in the current study to treat C2C12 cells are higher in relative comparison to that of the plasma concentrations of CBS−/+mouse models, our findings are more relevant to the severe HHcy conditions (homocystinuria) as well as acute model of HHcy." (PMID 25608649, 2015). "The cystathionine β-synthase (CBS) gene has been shown to be related to homocystinuria." (PMID 26667307, 2015). "Homocystinuria (HCU; McKusick 263200) is an inherited deficiency of cystathionine β-synthase (CBS)." (PMID 24422943, 2014). "Furthermore, H2S levels and CBS enzyme activity were shown to be reduced in homocystinuria and liver cirrhosis." (PMID 24260346, 2013). "Inactivation of CBS results in classical homocystinuria (HCU), which is the most common inherited defect in sulfur amino acid metabolism and is characterized biochemically by severe increases in plasma and tissue levels of Hcy, methionine and S-adenosylhomocysteine (AdoHcy)." (PMID 20638882, 2010). "Our study is the first to report the dramatic consequences of the T236N mutation on the stability and enzymatic function of CBS protein, contributing to a better understanding of the complex mechanisms of those certain CBS mutations that lead to homocystinuria pyridoxine non-responsiveness." (PMID 38790892, 2024). "In normal fibroblast lines, CBS is up to 85% saturated with PLP, whereas saturation is decreased in mutant fibroblast lines from homocystinuria patients, especially those unresponsive to B6." (PMID 34251022, 2021). "Accordingly, the lack of CBS elevates the level of homocysteine and methionine and lowers the concentrations of cystathionine and cysteine in the plasma of homocystinuria patients." (PMID 32245022, 2020). "A lack of cystathionine synthase (CBS) leads to elevated plasma concentrations of homocysteine, an inherited autosomal recessive metabolic disease named homocystinuria." (PMID 26035828, 2015). "Classic homocystinuria was first described in individuals with neurocognitive and Marfanoid features who were found to have increased urinary excretion of methionine and Hcy, and liver biopsies later revealed a lack of CBS activity." (PMID 37994477, 2023). "However, according to the clinical observation and the genotyping of all Qatari patients suffering from homocystinuria predict the absence of CBS enzymatic activity and nonresponsiveness to vitamin B6 supplements." (PMID 32245022, 2020). "Since the focus of the present article is CBS inhibition and CBS inhibitors (as opposed to CBS activation or CBS replacement therapy), the reader is referred to extensive expert reviews on the genetic basis, diagnosis, pathogenesis and experimental therapy of homocystinuria." (PMID 32365821, 2020).
hyperhomocysteinemia (79 papers, 2005 to 2026). A serious metabolic condition caused by mutations in the MTHFR gene, medications, or nutritional deficiency. "The effects of severe hyperhomocysteinemia (HHcy) were studied in subjects (rats and humans) with homozygous deficiency in cystathionine-beta-synthase (CBS), an enzyme involved in homocysteine conversion to cysteine." (PMID 41149254, 2025). "CBS deficiency leads to hyperhomocysteinemia and impaired production of antioxidants such as hydrogen sulfide." (PMID 38419709, 2024). "Hyperhomocysteinemia is a well-known risk factor for cardiovascular disease and leads to downregulation of CBS, CSE, and 3-mercaptopyruvate sulfurtransferase (3-MST) in the kidneys and liver, resulting in decreased H2S plasma levels." (PMID 36977089, 2023). "In a study conducted on CBS (cystathionine beta-synthase) deficient mice, an inherited metabolic disease inducing severe hyperhomocysteinemia, several indicators of oxidative stress were notably increased." (PMID 38133363, 2023). "Cystathionine-β-synthase (CBS) is highly expressed in the liver, and deficiencies in Cbs lead to hyperhomocysteinemia (HHCy) and disturbed production of antioxidants such as hydrogen sulfide." (PMID 37108182, 2023). "In this regard, hyperhomocysteinemia, a condition caused by the lack of CBS expression and characterised by elevated levels of plasma homocysteine, has been associated with DB pathogenesis." (PMID 35453313, 2022). "CBS enzyme deficiency can lead to hyperhomocysteinemia, leading to premature development of cardiac and cerebrovascular disease." (PMID 35152560, 2022). "A deficiency in CBS activity leads to markedly increased plasma homocysteine (Hcy) levels, namely severe hyperhomocysteinemia (HHcy), in human and rodents." (PMID 35681432, 2022). "Mutations involving cystathionine beta synthase and methylenetetrahydrofolate reductase result in hyperhomocysteinemia and homocysteinemia." (PMID 34221548, 2021). "While few, if any, studies have proven a cardioprotective role for CBS, mutations in this protein can lead to hyperhomocysteinemia and an increased risk for cardiovascular disease along with accelerated atherosclerosis." (PMID 33806545, 2021). "The most characteristic feature of CBS-deficient mice is a severe degree of hyperhomocysteinemia (an increase in plasma homocysteine concentration from the physiological 5 μM to approximately 500 μM)." (PMID 32365821, 2020). "CBS is view as particularly important as its deficiency is the most common cause of hyperhomocysteinemia." (PMID 31058853, 2019). "CBS deficiency was identified as a genetic factor that resulted in elevated levels of Hcy or hyperhomocysteinemia." (PMID 30916171, 2019). "Hyperhomocysteinemia due to cystathionine beta synthase (CBS) deficiency is associated with diverse cognitive dysfunction." (PMID 30172984, 2018). "In cystathionine beta-synthase-deficient mice, an animal model for hyperhomocysteinemia, elevated serum homocysteine levels inhibited intravascular VLDL lipolysis, resulting in elevated serum VLDL levels." (PMID 30153273, 2018). "In vivo studies using CBS+/−, a model for hyperhomocysteinemia, and sibling CBS+/+ control mice revealed that deficiency of CBS upregulates cardiac CSE, plausibly by inducing SP1." (PMID 28623294, 2017). "Hyperhomocysteinemia causes downregulation of CBS and CSE, resulting in H2S depletion, which in turn leads to vascular damage, vascular disease, and subsequently to deterioration of endothelial function." (PMID 28753969, 2017). "For one, hyperhomocysteinemia has been known to be associated with insufficient stimulation of CBS activity." (PMID 27047940, 2016). "In a study on 24 patients with hyperhomocysteinemia due to CBS deficiency, six patients had a thrombotic event, only one was a carrier for FVL and three were carrier of MTHFR 677C > T mutation." (PMID 25516723, 2014).
hyperhomocysteinemia (continued). "MTHFR 677 TT variant along with MS 2756 AA genotype, and MTHFR 677 TT variant along with CBS 844ins68 AA genotype also showed significantly increased risk for hyperhomocysteinemia, (ORs, 19.1 and 14, respectively)." (PMID 22470444, 2012). "We analyzed six SNPs in enzymes involved in homocysteine metabolism (i.e., MTHFR C677T and A1298C; CBS T833C, G919A and 844ins68, and MS A2756G) in 872 healthy study subjects and studied their influence on the risk of hyperhomocysteinemia in this population." (PMID 22470444, 2012). "Severe hyperhomocysteinemia is due to rare genetic defects resulting in deficiencies in cystathionine beta synthase, MTHFR, or in enzymes involved in methyl-B12 synthesis and homocysteine methylation." (PMID 18201384, 2008). "Mutation or deficiency in CBS is associated with severe homocysteinemia at systemic level." (PMID 37749555, 2023). "Certainly, the presence of inactivating mutations in the CBS gene results in hyperhomocysteinemia." (PMID 32093603, 2020). "Evidence from several preclinical models showed that the depletion of H2S levels is implicated in bone loss; data were reported in ovariectomized mice, in H2S-deficient CBS+/− mice, in a model of H2S-deficiency linked to diet-induced hyperhomocysteinemia, and in methionine-restricted fed rats." (PMID 31652532, 2019). "Hyperhomocysteinemia may be related to genetic defects, such as CBS deficiency or thermolabile variant of MTHFR, or to deficiencies of related B group vitamins." (PMID 28863787, 2017). "Mutations in CBS cause hyperhomocysteinemia, which is marked by elevated levels of homocysteine." (PMID 24320595, 2013). "Severe homocysteinemia was also observed in mouse models for CBS deficiency; whereas CBS−/− mice die a few weeks after birth, CBS −/+ mice were established as a model for CBS deficiency." (PMID 23117410, 2012). "Deficiency in cystathionine β-synthase (CBS), the first and rate-limiting enzyme of the transsulfuration pathway, is the major cause of severe hyperhomocysteinemia followed by genetic defects of folate and cobalamin metabolism that is involved in Hcy remethylation." (PMID 21837278, 2011). "Insufficiency in CBS activity may lead to hyperhomocysteinemia, which is considered to be an independent risk factor for arteriosclerosis." (PMID 16375773, 2005). "Although accumulation of amino acid homocysteine leading to hyperhomocysteinemia may occur due to defects in different enzymes, evidence shows that CBS 844ins68 mutation and VNTR polymorphisms of the CBS gene are independent risk factors for AD development in subjects aged 75 years or more." (PMID 36764968, 2023). "Moreover, according to a meta-analysis, the c.833T>C(p.Ile278Thr) polymorphism (a 68 bp insertion at 844 in the exon 8, which produces a form of CBS that has lower specific activity and produces mild hyperhomocysteinemia) is associated with a significantly higher risk of stroke." (PMID 32365821, 2020). "Compared with CBS-deficient mice in the previous research, the results of this study may be more precise and accurate in explaining the molecular mechanism of hereditary hyperhomocysteinemia etiology." (PMID 33054837, 2020). "Therefore, it appears that decreased CBS activity may also favor the induction of hyperhomocysteinemia by choline deficiency in rats fed with 25S diet." (PMID 25250392, 2014). "A large number of polymorphisms have been reported in the CBS gene, some of which impair its activity and among these, a T833C polymorphism in cis with a 68 bp insertion at 844 in the exon 8 is found to be associated with mild hyperhomocysteinemia in different ethnic groups." (PMID 16375773, 2005). "Infertility in CBS-KO individuals occurs due to the resulting hyperhomocysteinemia or due to the action of another factor in the uterine environment of CBS-KO homozygotes." (PMID 38933705, 2024).
hyperhomocysteinemia (continued). "As CBS converts homocysteine to H2S in the transsulfuration pathway, knockdown of CBS led to hyperhomocysteinemia and a reduction in H2S and GSH levels." (PMID 40405983, 2024). "A subset of patients displaying homocysteinemia exhibited diminished CBS activity and substantial cardiovascular disability." (PMID 37237961, 2023). "Hyperhomocysteinemia can cause downregulation of CSE and CBS, thereby causing production of H2S is injury." (PMID 36727029, 2022). "Since hyperhomocysteinemia occurs often in the context of lowered activity of the H2S generating enzyme CBS, it is worth dedicating a whole section on this disorder." (PMID 35204708, 2022). "In the mouse model of CBS (+/−) hyperhomocysteinemia, homocysteine thiolactone, a highly reactive homocysteine metabolite has been demonstrated to directly affect eNOS by N- homocysteinylation and consequently reducing the bioavailability of NO." (PMID 35204708, 2022). "Cystathionine beta synthase (CBS) catalyzes the first step of the transsulfuration pathway from homocysteine to cystathionine, and its deficiency leads to hyperhomocysteinemia (HHcy) in humans and rodents." (PMID 35681432, 2022). "Inhibition of CBS and MTHFR, along with deficiencies in folate and vitamin B12, are considered as the primary causes of hyperhomocysteinemia." (PMID 31938715, 2020). "Overall, our findings suggest that Cbs−/− mice have a better adaptive response to protect from prothrombotic effects of hyperhomocysteinemia than CBS−/− humans." (PMID 32612202, 2020). "We have generated CBS-KO rabbits with G307S mutation for the first time using the CRISPR/Cas9 system, and the model exhibits hyperhomocysteinemia and dyslipidemia on a normal chow diet." (PMID 33054837, 2020). "Low levels of the CBS gene lead to hyperhomocysteinemia, which was also discovered in earlier studies, indicating its effects on hypertension and stroke." (PMID 30916171, 2019). "Both CBS gene polymorphisms and the C667T and the A1298C SNPs in the MTHFR gene decrease the activity of the MTHFR enzyme leading to hyperhomocysteinemia." (PMID 30646578, 2019). "In contrast to CSE, CBS-catalyzed H2S-generating reactions are insensitive to the grade of hyperhomocysteinemia." (PMID 31885816, 2019). "Mutations in cystathionine beta synthase (CBS), an enzyme present at the branch point between the trans-sulfuration and remethylation pathways, are the basic cause of homocysteinemia." (PMID 30804341, 2019). "Concerning bone tissue, in the animal model of hyperhomocysteinemia (CBS−/− mice), the autosomal recessive disease involving CBS, higher levels of inflammation has been correlated to lower bone tissue." (PMID 31652532, 2019). "Plasma Hcy levels in CBS+/- mice were 3.46 times higher than that in CBS+/+ mice, indicating that hyperhomocysteinemia (HHcy) animal model was induced successfully." (PMID 29415998, 2018). "In Tg-I278TCbs-/- (a Cystathionine β-synthase (CBS) mouse model which exhibit extreme hyperhomocysteinemia) the expression of AS and GADD45 genes are induced." (PMID 26959487, 2016). "The decrease in activity of betaine-homocysteine S-methyltransferase (BHMT) and cystathionine β-synthase (CBS) in GAA-induced hyperhomocysteinemia was recovered by supplementation with betaine or spinach." (PMID 25250392, 2014). "This is further supported by decrease in the risk of hyperhomocysteinemia in various combinations of MTHFR 677TT with MS 2756AG variant and CBS 844ins68 AI variant." (PMID 22470444, 2012). "Protective effect towards hyperhomocysteinemia was observed with heterozygous (ancestral/insertion) genotype of CBS 844ins68 compared to homozygous ancestral type [OR (95% CI); 0.58 (0.34–0.99)]." (PMID 22470444, 2012). "Increased serum levels of homocysteine induce damage to endothelial cells in CBS −/+ mice and in human patients with homocysteinemia." (PMID 23117410, 2012). "CBS−/− knockout mice exhibit severe hyperhomocysteinemia and accumulate AdoHcy in all tissues tested." (PMID 21837278, 2011).